SPP1 (secreted phosphoprotein 1)
Diseases named in the same sentence as SPP1 in open-access papers (continued):
Sharing a sentence is not in itself a finding about the gene and the disease.
tumor (continued). "In the TCGA database, SPP1 expression was significant higher in most tumor tissues, but showed lower expression in KICH, PAAD, SKCM, and THYM, however, without statistical significance." (PMID 35067176, 2022). "Seven genes of the prognostic model (COPA, GPX7, ITGB5, MATN3, MCM7, MMP1, and SPP1) have been validated to be related to tumor progression, whereas the remaining three genes, BNDF, GADD45B, and LOX, need to be further analyzed." (PMID 35699863, 2022). "By comparing to the control group, tumours in the shEEF2K + vector group developed much slower, but this effect was abrogated by SPP1 overexpression (shEEF2K + SPP1 group)." (PMID 35184394, 2022). "According to our scRNA-seq data, most of the tumor cells either expressed S100P (23.95%) or SPP1 (60.05%), while only 10.01% and 5.98% tumor cells showed double negativity or double positivity, respectively." (PMID 35347134, 2022). "Collectively, these data suggest that SPP1+ TAMs are associated with unfavorable clinical outcomes in patients with ICC and correlate closely with immune infiltrates in the ICC tumor ecosystem." (PMID 35558087, 2022). "It has been shown that SPP1 can bind to CD44v6 and promote tumor cell proliferation and survival through JNK pathway." (PMID 35154316, 2022). "SPP1 is a phosphorylated glycoprotein secreted by tumor cells and other host cells, which has been reported to be closely associated with the invasion, metastasis, and proliferation ability of certain cancers." (PMID 36276156, 2022). "Since APOE was expressed in nearly 90% of TAMs, we focused on SPP1+ TAMs and found more interactions of CAFEndMT with SPP1+ TAMs than that with SPP1- TAMs in tumor samples." (PMID 36333338, 2022). "Within the stroma, SPP1 induced fibroblast reprogramming and activation toward a pro-inflammatory, pro-tumor phenotype." (PMID 34832904, 2021). "We further examined the expression of known tumor-promoting markers in these immune subpopulations, confirming that CD4_CXCL13, CD4_FOXP3, CD8_CXCL13, CD8_ISG15, Mac_C1QA, Mac_ISG15 and Mac_SPP1 cells were tumor-promoting immune cells." (PMID 35087839, 2021). "The tumor angiogenesis, cell migration, ECM receptor interaction, and tumor vasculature pathways were enriched in SPP1+ TAMs, whereas the complement activation and antigen processing and presentation pathways were significantly enriched in C1QC+ TAMs." (PMID 34295336, 2021). "Through qPCR detection, we found that overexpression of SPP1 promoted the expression of a series of tumor stem cell markers." (PMID 33996808, 2021). "SPP1+ and CXCL5+ Mφ (clusters 6 and 7) clusters were enriched in tumor tissues and therefore were designated as tumor‐associated macrophages (TAMs)." (PMID 34185431, 2021). "SPP1 gene is reported to participate in many pathological and biological processes, including inflammation, tissue remodeling, immunity angiogenesis, tumor development and metastasis." (PMID 33996808, 2021). "Primary tumor growth and metastatic outgrowth can be suppressed by ablation of SPP1, a downstream target of GLI2, emphasizing its role in promoting tumor aggressiveness." (PMID 34888306, 2021). "But the clinical significance and biological roles of SPP1 in tumor metastasis are still incompletely understood." (PMID 34721759, 2021). "Our results demonstrated that CD44 within ER+ tumor cells interacted with SPP1, also known as osteopontin (OPN) with macrophages." (PMID 34685653, 2021). "Compared with the normal samples, ATG10, PRKCD, and SPP1 were highly expressed in the tumor samples." (PMID 34631695, 2021). "Compared with the paracancerous tissues, the expression of CXCL13(P = 0.0093), IDO1(P = 0.0068), PI3(P = 0.0161), SPP1(P = 0.0122) in tumor tissues was significantly increased, while TRIM22(P = 0.0342) was significantly decreased." (PMID 34736480, 2021).
tumor (continued). "A six-gene risk score, the SCCHN TMI (SCCHN-tumor matrisome index: composed of MASP1, EGFL6, SFRP5, SPP1, MMP8 and P4HA1) was constructed and used to stratify patients into risk groups." (PMID 34830910, 2021). "Our scATAC‐seq analysis of myeloid cells in adjacent and tumor tissues was also able to recover the SPP1+ TAMs (cluster 3)." (PMID 34185431, 2021). "The results showed that the expression of C1QC, FN1, and SPP1 increased significantly in TAMs, which indicated that the tumor microenvironment most likely induced their high expression in macrophages." (PMID 34804043, 2021). "Conversely, the main metabolism pathway for SPP1+ macrophage was glycolysis which contributed to tumor metastasis by promoting angiogenesis and matrix remodeling." (PMID 34804043, 2021). "The results showed that mRNA levels of ATG10, IL18RAP, PRKCD, SLC11A1, and SPP1 differed between tumor tissues and normal tissues in most of the 33 cancer types." (PMID 34631695, 2021). "Among them, due to traits such as specific expression sites and promoting tumor immune tolerance, SPP1 showed significant potential as an ideal target for adjuvant immunotherapy and for improving the efficacy of immunotherapy." (PMID 34804043, 2021). "To find new potential checkpoints, we investigated the cell-cell communications between tumor-promoting immune cells (CD4_CXCL13, CD4_FOXP3, CD8_CXCL13, CD8_ISG15, Mac_C1QA, Mac_ISG15, Mac_SPP1 and cDC3_LAMP3) and the ductal epithelial cells." (PMID 35087839, 2021). "Within the tumor microenvironment induced by C. parvum, upregulated expression of immune suppressive factors such as ARG1 and SPP1 probably indicates the presence of tumor promoting M2 TAMs." (PMID 34946170, 2021). "SPP1 has also been demonstrated in mice and humans to affect tumor cell migration, adhesion, and invasion, indicating its possible use as a diagnostic biomarker and potential therapeutic target in cancer." (PMID 33461176, 2021). "Our study established a novel six‐gene (APOC1, GLTP, ISG20, SPP1, SLC24A3 and UPP1) signature that was closely associated with the immune response and tumour immune microenvironment." (PMID 34498424, 2021). "Secreted phosphoprotein 1 (SPP1), also recognized as osteopontin (OPN), a secreted chemokine-like glycophosphoprotein, is a cardinal mediator of tumor-associated inflammation and facilitates metastasis." (PMID 34721759, 2021). "Our findings were in agreement with previous data which suggested that SPP1 were mainly released from tumor cells and was highest expressed in bone metastatic site." (PMID 34721759, 2021). "The GSEA results suggested that subgroups of patients divided by C1QC+ and SPP1+ TAMs gene signatures showed different anti- or pro-tumor state." (PMID 34295336, 2021). "Our results showed that the hub genes COL1A1, THBS2, and SPP1 were also able to alter cellular components in the tumor microenvironment, and that they had an axial relationship with PD-L1 expression." (PMID 33345281, 2021). "SPP1 is a crucial extracellular matrix component, secreted by multiple kinds of cell types including tumor cells, immune cells, fibroblasts, osteoclasts, smooth muscle, lymphocytes, and epithelial cells." (PMID 34721759, 2021). "For example, knockdown of SPP1/Opn in tumor cells promoted polarization of macrophages to an anti-tumor phenotype." (PMID 34832904, 2021). "By analysis of single-cell RNA sequencing data, MIT score was positively correlated with the proportion of tumor-promoting immune cell clusters, especially the Mac_C1QA, Mac_SPP1 and Mac_ISG15 population." (PMID 35087839, 2021). "Secreted SPP1 interacts with integrin and CD44, which are associated with cellular transformation and tumor progression." (PMID 34234236, 2021). "Bulk RNAseq data from TCGA showed that SPP1 expression was significantly higher in tumor tissues than normal tissues." (PMID 34857857, 2021).
tumor (continued). "Using qRT-PCR, we validated that their transcriptions in our GC tumor tissue were upregulated except SPP1 and FN1, which correlated with tumor relapse and predicts poorer prognosis in GC patients." (PMID 34126961, 2021). "Previous research suggests that the Spp1:Cd44 signalling axis acts as an immune checkpoint thus, inducing host tolerance during tumour formation." (PMID 33686070, 2021). "We compared the expression of SPP1 in LUAD tumor and normal tissues, and in samples with wild-type and mutant EGFR." (PMID 34178613, 2021). "On the other hand, CXCL13 recruits CXCR5+ CD68+ macrophages secreting SPP1, which triggers tumor cell migration through the EMT pathway in lung cancer." (PMID 34947813, 2021). "SPP1_CD44 interaction was upregulated during the transition from ductal-normal cells to ductal-tumor cells but was downregulated during the malignant transition." (PMID 35087839, 2021). "GEPIA-generated box plot was used to compare the tissue-based expression patterns of SPP1 between HCC (TCGA tumor) and paired normal adjacent tissue samples (TCGA normal + GTEx normal)." (PMID 34977039, 2021). "Spp1 is up-regulated specifically in Avd during tumourigenesis and ultimately also highly expressed by the tumour." (PMID 33686070, 2021). "Secreted phosphoprotein 1 (SPP1) participated in various biological processes in many cancers, including immune response, tumor progression, and prognosis." (PMID 34977258, 2021). "Fibrotic lung-derived fibroblasts produce high level of FN1 and the secreted phosphoprotein 1 (SPP1) that chemoattract tumor cells and inhibit their apoptosis by binding to the common integrin αv receptor, expressed by tumor cells." (PMID 33731188, 2021). "Our study established a novel six‐gene (APOC1, GLTP, ISG20, SPP1, SLC24A3 and UPP1) signature that was closely associated with the immune response and the tumour immune microenvironment." (PMID 34498424, 2021). "SPP1 can bind and activate multiple downstream signaling pathways, which can activate tumor growth and invasion and limit the antitumor function of immune cells." (PMID 34977258, 2021). "Through co‐expression analyses, we verified that APOC1, ISG20 and SPP1 had notably strong correlations with tumour‐infiltrating immune cells, highlighting new directions for further research." (PMID 34498424, 2021). "In this study, we confirmed that SPP1 was elevated in GAC tissues and cell lines, and SPP1 overexpression was positively associated with tumor size, nodal status, and histological grade of GAC patients." (PMID 34367279, 2021). "By analyzing the correlation between five genes and tumor microenvironment, we found that SPP1, PRKCD, and SLC11A1 were highly positively correlated with macrophages." (PMID 34631695, 2021). "To determine the function of tumor-expressed OPN in tumor–T cell interaction, we knocked out Spp1 in CT26 cells." (PMID 33670921, 2021). "We concluded that SPP1 is significantly upregulated in tumor tissues and can become a prognostic biomarker for HNSCC." (PMID 34977258, 2021). "SPP1 gene is therefore involved in cell adhesion and other similar signaling pathways and promotes tumor progression and metastasis." (PMID 33996808, 2021). "Early studies reported tumor or plasma levels of secreted phosphoprotein 1(SPP1, also known as osteopontin, OPN) were associated with an aggressive phenotype in lung cancer." (PMID 34234236, 2021). "SPP1 was upregulated in macrophage derived from tumor samples compared with that from normal tissues; we reasoned that SPP1 was a specific TME-induced expression program in TAMs." (PMID 34676217, 2021). "The GSEA results suggested that subgroups of patients divided by C1QC+ and SPP1+ TAMs gene signatures showed different anti- or pro-tumor states." (PMID 34295336, 2021).
tumor (continued). "All the genes identified to activate the tumor microenvironment pathway were highly upregulated at day 93 PI except secreted phosphoprotein 1 (SPP1), Indoleamine 2,3-dioxygenase 1 (IDO1), UBD and CD274, which were also highly upregulated at day 45 PI." (PMID 34946170, 2021). "Integrin receptors belong to heterodimeric transmembrane glycoproteins, which binds to SPP1 in an RGD-dependent way regulating tumor cell adhesion, migration, proliferation, and survival." (PMID 34721759, 2021). "Osteopontin (OPN), encoded by SPP1, is a widely distributed extracellular matrix protein, which is involved in various biological processes, including tumor progression, bone metabolism, and inflammation." (PMID 32856055, 2020). "This work shed novel lights on the SPP1 function and receptor interactions in tumor immune infiltration." (PMID 33324676, 2020). "In summary, our data revealed a previously uncharacterized mechanism that increased SPP1 expression correlated with poor prognosis and promoted tumor progression." (PMID 33324676, 2020). "As a crucial gene in tumor pathogenesis, SPP1 is related to the stem cell characteristics of HCC and is involved in PD-L1-mediated immune escape in HCC." (PMID 33072587, 2020). "Expression levels of HCC markers revealed a marked overexpression of Afp in tumours from WT compared to Spp1−/− animals." (PMID 32281248, 2020). "Collectively, such results suggested the vital part of SPP1 and its potential as a predictor in the regulation of immune infiltration, tumor prognosis, progression and metastasis." (PMID 33324676, 2020). "BGN and SPP1 are essential components of the extracellular matrix, which has a critical role during the migration and progression of tumor cells." (PMID 33362844, 2020). "Previous reports had demonstrated that SPARC and SPP1 were able to suppress the migration of DCs to lymph nodes, which would result in the accumulation of DCs at primary tumor site." (PMID 33240930, 2020). "SPP1 exerts its effects by interacting with receptors that ultimately lead to tumor progression, invasion, and metastasis." (PMID 33324676, 2020). "SPON2 participates in activation of immune response and recruitment of inflammatory cells, whereas SPP1 along with other pro-inflammatory factors contributes to tumor growth, angiogenesis by stimulating VEGF and macrophage recruitment." (PMID 33322258, 2020). "A significantly low DNA methylation were noted for SPP1 relative to high expression levels in tumor tissues, while high DNA methylation and low expression for LCAT (P < 0.0001)." (PMID 32514252, 2020). "Alternatively, SPP1 transcripts were detected in multiple tumour samples (42/58), consistent with previous reports." (PMID 32503462, 2020). "qRT-PCR results showed that the mRNA expression of COL1A1, IGF1, COL5A1, CXCL12, PTEN, and SPP1 were also significantly differently expressed in normal samples and tumor samples." (PMID 32641130, 2020). "For better exploring the SPP1 mechanism in promoting tumor progression and poor prognosis, we investigated and identified somatic mutations and CNV in COAD, HNSC, LUAD, and LUSC." (PMID 33324676, 2020). "It was suggested that, the abundance of tumor infiltration of B memory cells and activated DCs was negatively correlated with SPP1 in COAD, HNSC, and LUSC." (PMID 33324676, 2020). "From the cohort of matched patients’ tumour tissues (n = 130), 100 were available for SPP1 gene expression analysis (by qPCR) and 116 were available for OPN protein analysis (by IHC)." (PMID 31996744, 2020). "SPP1 expression was weakly related to tumor purity together with the CD4 + T cell, macrophage, and DC infiltrating degrees in LUSC." (PMID 33324676, 2020). "Intensive research on contribution of SPP1 in pathophysiology of cancer has unveiled the multifaceted role of SPP1 in tumor progression." (PMID 33324676, 2020).
tumor (continued). "Our study found that SPP1 was significantly overexpressed in tumor samples, and its univariate Cox analysis in the discovery cohort showed it to be a risk factor for patients with THCA." (PMID 33193731, 2020). "Accordingly, down-regulation of SPP1 reduced tumor cells invasion and vimentin expression, but increased the level of GFAP, a marker of differentiated astrocytes." (PMID 33066172, 2020). "For elucidating the possible mechanism of action by which SPP1 affected tumor prognosis, we investigated and identified correlated somatic mutations, CNV, and genes expression in four selected cancers." (PMID 33324676, 2020). "SPP1 is a secreted calcium binding phosphorylation protein, which can activate many kinds of signaling pathways, promote tumor growth, metastasis, and angiogenesis and regulate the expression of various carcinogenic and angiogenic molecules." (PMID 32595698, 2020). "We found that overexpression of the identified driver genes, stratifin (SFN) and SPP1, correlates with tumor grade and poor survival in HCC and promotes HCC cell proliferation." (PMID 33221766, 2020). "In summary, we revealed an overexpression of ECM components, which are associated with enhanced migratory capacities of tumour cells (TNC, FN1), resistance to chemotherapy (COL11A1, SPP1) and adverse outcome (COL11A1, TNC, FN1) in other primaries." (PMID 32878206, 2020). "SPP1, also known as Osteopontin (OPN), is an important secretory phosphorylated glycoprotein producted by both tumor cells and a variety of host cells, including multiple immune cells, osteoclasts, fibroblasts, endothelial, smooth muscle and epithelial cells." (PMID 31620371, 2019). "Silencing the expression of SPP1 using siRNA decreased the NSCLC tumor volume and weight in mice demonstrated it as a promising therapeutic target." (PMID 31681566, 2019). "Among these, ITGB8, RELN, and SPP1 were the top tumor-promoting candidates significantly downregulated (FDR < 0.05) by YBX1 knockdown in the ECM-receptor interaction pathway." (PMID 31481087, 2019). "SPP1, a tumor-related extracellular matrix protein, has been reported to be involved in the pathogenesis of BRC." (PMID 31921672, 2019). "SPP1 is a secreted chemokine-like glycophosphoprotein participated in tumor cell proliferation, invasion, and metastasis." (PMID 31620371, 2019). "SPP1 exhibited significantly higher expression in tumor samples than in adjacent normal samples, whereas LCAT exhibited significantly decreased expression in tumor samples (P < 0.0001)." (PMID 31695766, 2019). "SPP1-induced interaction between tumor cells and stromal cells promotes tumor progression and angiogenesis, and drug resistance." (PMID 31620371, 2019). "Matusan and colleagues found high levels of SPP1 in ccRCC was significantly correlated with tumor size, Fuhrman nuclear grade, pathological stage, and Ki-67 proliferation index." (PMID 31481087, 2019). "SPP1 exhibited significantly higher expression in tumor samples than in corresponding normal samples (P < 0.0001)." (PMID 31695766, 2019). "We conclude that Tg6F alters levels of specific oxidized lipids and 25-OHC to modulate Notch pathways and Spp1, which alter small intestine immune cells, leading to similar changes in lung that reduce tumor burden." (PMID 29899427, 2018). "We therefore accessed the TCGA-COAD database and compared SPP1 mRNA expression levels in CRC tumour samples (n = 101) and healthy colon tissue samples (n = 19)." (PMID 30373147, 2018). "Secreted phosphoprotein 1 (SPP1, also called osteopontin) has functions in tumorigenesis, tumor progression, and metastasis in numerous cancers." (PMID 28225791, 2017). "Secreted phosphoprotein 1 (SPP1) is a kind of important cytokine, which has been proved to play an important role in tumor progression and metastasis by regulating the cell signaling." (PMID 28148898, 2017).